PTH (parathyroid hormone)
Diseases named in the same sentence as PTH in open-access papers (continued):
Sharing a sentence is not in itself a finding about the gene and the disease.
left ventricular hypertrophy (48 papers, 2009 to 2025). Enlargement of the LEFT VENTRICLE of the heart. "Prolonged elevations in PTH levels have been linked to vascular endothelial dysfunction, insulin resistance, left ventricular hypertrophy, and increased arterial stiffness." (PMID 41269693, 2025). "As a result, PTH levels rise, which is connected to cardiotoxicity-causing left ventricular hypertrophy." (PMID 39246913, 2024). "This study aimed to investigate the relationship and underlying mechanisms between parathyroid hormone (PTH) and salt intake in the development of left ventricular hypertrophy (LVH)." (PMID 37842376, 2023). "On the other hand, our group has recently demonstrated that, in patients with stable coronary artery disease, PTH is associated with the presence of left ventricular hypertrophy." (PMID 35887917, 2022). "Elevation of serum PTH causes left ventricular hypertrophy, myocyte/capillary mismatch, and cardiac fibrosis." (PMID 31597282, 2019). "The other important role of magnesium is the beneficial effect on decreasing intact parathyroid hormone, which is considered an independent risk factor for vascular calcification, left ventricular hypertrophy and mortality in CKD patients." (PMID 27023783, 2016). "In addition, elevated PTH has been implicated in the pathogenesis of left ventricular hypertrophy, renal anemia, and immune dysfunction." (PMID 39430172, 2024). "Plasma PTH levels exhibit a close association in elderly individuals with cardiac aging phenotypes such as left ventricular hypertrophy, suggesting that plasma PTH could serve as a biomarker of cardiac aging." (PMID 39872891, 2023). "The elevation of PTH levels is also associated with left ventricular hypertrophy and CV events." (PMID 33104746, 2020). "On the other hand, PTH has positive inotropic and chronotropic effects and favors the development of left ventricular hypertrophy." (PMID 37959184, 2023). "Recent research has indicated that PTH can also profoundly impact the cardiovascular system, potentially leading to hypertension, left ventricular hypertrophy (LVH), heart failure, and other cardiovascular diseases." (PMID 37842376, 2023). "High phosphate diet increased blood pressure, plasma renin activity, angiotensin II, left ventricular hypertrophy, and PTH in rats.The addition of lanthanum carbonate, a phosphate binder reversed these changes." (PMID 36364791, 2022). "PTH may also lead to the impairment of left ventricular diastolic function, and it has been described as an independent predictor of left ventricular hypertrophy (LVH) in HD patients." (PMID 39408018, 2024). "Furthermore, PTH has been linked to the pathophysiology of heart failure and left ventricular hypertrophy, although not all the studies confirm this relationship." (PMID 40806886, 2025). "However, enhanced FGF-23 and PTH levels may also favor vascular damage, and left ventricular hypertrophy." (PMID 27171378, 2016). "Phosphorus has been shown to be an independent risk factor for cardiovascular disease, including increased intima media thickness, vessel stiffness, and left ventricular hypertrophy; PTH per se may contribute to vascular injury via mechanisms other than its effect on calcium-phosphorus homeostasis." (PMID 24198729, 2013). "This may result from the noncalcemic effects of PTH, such as atherogenesis by vascular calcification, left ventricular hypertrophy, and direct effects on vascular smooth muscle cells." (PMID 37286864, 2023). "These negative effects are the consequence of increases in the parathyroid hormone (PTH) level, which can lead to left ventricular hypertrophy." (PMID 35162272, 2022).
heart failure (47 papers, 2010 to 2025). Inability of the heart to pump blood at an adequate rate to meet tissue metabolic requirements. "Some studies have reported that the levels of PTH, which is associated with endothelial dysfunction, are higher in the systemic circulation of patients with heart failure." (PMID 31261815, 2019). "An elevated PTH level is associated with increased N-terminal pro-brain natriuretic peptide, a marker of left ventricular wall stress, and increased risk of heart failure." (PMID 29554879, 2018). "Serum 25OHD and/or PTH levels have been shown to be independently associated with all cause and cardiovascular mortality in adult patients with heart failure." (PMID 26955207, 2016). "Elevated serum phosphate concentrations have been associated with cardiovascular events including heart failure through its interactions with parathyroid hormone, vitamin D, and fibroblast growth factor 23 in some studies." (PMID 27716206, 2016). "There are also studies, claiming that there are higher levels of parathyroid hormone in the systemic circulation of patients with heart failure, which is associated with endothelial dysfunction." (PMID 24524078, 2014). "In particular, elevated PTH levels have been positively associated with platelet indices in women with symptomatic heart failure, and PTHrP, by interacting with PTH1R on human platelets was shown to potentiate platelet aggregation in response to different stimuli." (PMID 41109132, 2025). "To gain further insight into the endocrine mechanisms that may underlie bone loss in heart failure, we analyzed serum electrolytes, biochemical bone markers, and PTH levels." (PMID 41515999, 2025). "High PTH was also associated with increased risk of heart failure and venous thromboembolism." (PMID 29088221, 2017). "This explains why elevated PTH is frequently associated with increased circulating aldosterone in patients with heart failure and supports the hypothesis that PTH might concur with aldosterone in causing worsening of cardiac function in these patients." (PMID 29056965, 2017). "Oncostatin M is part of the interleukin-6 (IL-6) family and regulates remodeling and PTH effects in bone as well as cardiac FGF23 production in heart failure via glycoprotein gp130." (PMID 37225713, 2023). "The relationship between plasma fibroblast growth factor 23, PTH and 25-OHvitamin D with heart failure in a population-based study has been undertaken." (PMID 39076268, 2023). "Circulating parathyroid hormone (PTH) concentrations increase in heart failure (HF) and are related to disease severity." (PMID 36286286, 2022). "Inflammatory mediators and PTH are known to play a critical role in the ventricular “remodeling” process and in the prognosis of heart failure." (PMID 36945996, 2022). "The relationship between PTH and heart failure (HF) has been pointed out according to current evidence." (PMID 36286286, 2022). "PTH was reduced by 20 pg/ml in our vitamin D3 group; other studies have had similar findings in heart failure to a lesser magnitude." (PMID 29084522, 2017). "Interestingly, the authors of the Scientific Statement note that there is evidence for PTH as a biomarker in heart failure and that consequently, there is a potential for PTH to be used as a prognostic marker in the Fontan circulation." (PMID 39860501, 2025). "As noted in that article, a PTH of 65 pg/mL is the upper limit of normal, and a recent commentary reported that a PTH > 65 pg/mL is associated with increased risks of heart failure and CVD death, but not an all-cause mortality rate." (PMID 37189612, 2023). "Vitamin D has been shown to reduce PTH and inflammatory mediators, which may be protective for remodeling in patients with heart failure." (PMID 36945996, 2022). "During heart failure, a calcium deprivation occurs inducing PTH release, and the increased levels of the hormone could contribute to maladaptive responses, bearing important clinical and therapeutic implications." (PMID 30662585, 2018).
heart failure (continued). "Additionally, PTH levels in heart failure patients are elevated compared to healthy adults, suggesting that PTH dysregulation is a component in the complex pathology of heart failure." (PMID 29084522, 2017). "This complex interplay of salt with aldosterone and PTH might contribute to the development and progression of organ damage in patients with primary aldosteronism or primary hyper-PTH, in patients with heart failure, and in subjects with dietary salt excess." (PMID 29056965, 2017). "A disturbed vitamin D–parathyroid hormone (PTH)–calcium axis may play a role in the pathogenesis of heart failure." (PMID 23781303, 2012). "Therefore, the interactions between the sST2 and VD/PTH axis that control fibrosis and inflammation within the heart may control heart failure progression." (PMID 38161941, 2023). "An attenuation of the renin–angiotensin system and the secretion of parathyroid hormone (PTH) have been observed in individuals with elevated blood pressure, as well as heart failure, following treatment with vitamin D (calcitriol)." (PMID 39337248, 2024). "This interaction between aldosterone and PTH could have clinical relevance because it could lead, on the one hand, to cardiac structural and functional changes that facilitate development and progression of heart failure and, on the other hand, to decreased bone mineral density and strength." (PMID 29056965, 2017). "Several signaling pathways, including inflammatory mediators, PTH, vitamin D, and WNT-signaling, are major upstream pathways that regulate RANKL expression in general, but little is known which signaling pathway activates RANKL production in heart failure." (PMID 41515999, 2025). "Our study suggests that daily vitamin D3, used to replete insufficient stores, may safely improve hormonal factors in heart failure patients like 25(OH)D, BNP, and PTH as well as inflammation." (PMID 29084522, 2017). "Vitamin D status may influence heart failure (HF) patient outcomes by affecting b-type natriuretic peptide (BNP), parathyroid hormone (PTH), and enhancing cardiac contractility." (PMID 29084522, 2017). "In our study, the congestion related alterations in USG and DW-MRI investigations were also evident among patients with PTH without symptom and clinically overt heart failure." (PMID 20663149, 2010). "However, serum PTH levels in TAC mice were not changed, 6 weeks post-surgery, suggesting that PTH is not driving the bone phenotype in mice with heart failure." (PMID 41515999, 2025).
osteitis fibrosa cystica (47 papers, 2009 to 2025). "The persistent elevation of parathyroid hormone (PTH) causes the development of osteitis fibrosa cystica and osteoarthritis." (PMID 37447174, 2023). "Brown tumors are a rare variant of osteitis fibrosa cystica that results from sustained high levels of parathyroid hormone in CKD." (PMID 36819315, 2023). "Very high PTH levels (≥585 pg/mL) are usually associated with osteitis fibrosa, while very low PTH levels (<100 pg/mL) are associated with adynamic bone disease." (PMID 32961953, 2020). "The most severe form of hyperparathyroid bone disease is osteitis fibrosa cystica (OFC) caused by massive bone resorption mediated by parathyroid hormone (PTH)." (PMID 31752733, 2019). "Osteitis fibrosa cystica (OFC) is a skeletal disorder caused by a surplus of parathyroid hormone (PTH) from overactive parathyroid gland(s)." (PMID 23259108, 2012). "However, in patients with higher PTH (> 600 pg/mL), the leading cause of fractures is most likely due to osteitis fibrosa, which is prone to developing fractures despite frequently increased trabecular bone mass." (PMID 40008355, 2025). "Rarely elevated PTH levels in PsHP may cause increased bone remodeling leading to hyperparathyroid bone disease." (PMID 22779017, 2012). "In rats, mature MCs accumulated at bone turnover sites, particularly at the bone–marrow interface after parathyroid hormone (PTH) treatment, preceding the onset of osteitis fibrosa." (PMID 41155275, 2025). "Patients with PHP are functionally "hypoparathyroid," but due to a normal PTH response in bone, they can present with hyperparathyroid bone disease (osteitis fibrosa cystica) due to elevated PTH levels." (PMID 39350885, 2024). "Below we describe the two most common histologic patterns, which derive from very high (osteitis fibrosa) and relatively low levels of PTH (ABD)." (PMID 37342799, 2023). "When assessing ROC analysis for PTH to discriminate high turnover/hyperparathyroid bone disease from other types of ROD, PTH had an AUC of 0.69, cut-off for PTH was set at 450 ng/ml." (PMID 34137924, 2021). "However, we believe that the continuation of severe vitamin D3 deficiency in combination with low serum levels of intact PTH induces an increase of osteoid due to mineralization loss and may induce an inappropriate activation of osteoclast and osteoblast leading to mild osteitis fibrosa." (PMID 33180218, 2020). "The patient also presented high levels of serum calcium and parathyroid hormone, hyperfunctioning parathyroid tissue, bilateral parenchymal nephropathy, and densitometry lower than expected, showing an advanced stage of osteitis fibrosa cystica." (PMID 26881146, 2016). "The skeletal presentation of parathyroid bone disease in rats following continuous delivery of PTH via an osmotic pump is remarkably similar to human parathyroid bone disease and includes osteitis fibrosa, as detailed below." (PMID 20200965, 2010). "Elevated PTH levels, especially in advanced CKD, often point towards secondary hyperparathyroidism, which can predispose patients to high-turnover bone disease, such as osteitis fibrosa." (PMID 40710560, 2025). "Furthermore, despite preserved skeletal responsiveness, prolonged PTH elevation can lead to bone complications such as osteitis fibrosa cystica." (PMID 41170251, 2025). "Osteitis fibrosa is a metabolic skeletal disorder characterized by increased osteoblast and osteoclast activity, leading to abnormal bone matrix formation secondary to elevated parathyroid hormone (PTH) levels." (PMID 40827148, 2025). "Osteitis fibrosa cystica results from longstanding exposure of bone to increased PTH levels." (PMID 40177730, 2025). "Conversely, consistently high levels of PTH may lead to the development of osteitis fibrosa, characterized by persistent osteoclastic activity and bone resorption, converging to a tremendous risk of fractures." (PMID 38785509, 2024).
osteitis fibrosa cystica (continued). "Associated skeletal manifestations have been shown to improve after controlling the serum PTH concentration, likely by mitigating the bone high turnover process (i.e., osteitis fibrosa) and improving the bone mineral density; however, the extraskeletal complications did not improve." (PMID 34408941, 2021). "Moreover, the specificity and sensitivity of 18F-NaF PET was superior to PTH to diagnose high turnover/ hyperparathyroid bone disease." (PMID 34137924, 2021). "Osteitis fibrosa has been reported to being developed on patients with very high PTH levels." (PMID 33180218, 2020). "Moreover, in advanced stages of CKD, the constantly increasing PTH stimulation of PTHR1 ultimately prevails over the skeletal hyporesponsiveness to the action of PTH, and high turnover bone diseases (osteitis fibrosa or mixed uremic osteodystrophy) develop." (PMID 31637056, 2019). "Hyperparathyroid bone diseases are characterized by high PTH and high ALP levels." (PMID 30149605, 2018). "Therefore, the KDIGO experts recommend maintaining serum PTH levels in a large range, from to 2–9 times the upper limit of the assay in HD patients to lower the risk of severe osteitis fibrosa and ABD and to favor survival, based on the U-shape survival curve associated with serum PTH level." (PMID 27756251, 2016). "The first report of this disease derived from very high PTH levels was made by von Recklinghausen in 1891 (Von Recklinghausen, 1891), but the full report of “osteitis fibrosa cystica” was not provided until 1936, by Albright and co-workers." (PMID 37342799, 2023).
atherosclerosis (45 papers, 2012 to 2025). A disease characterized by the build-up of fatty material and calcium deposition in the arterial wall resulting in partial or complete occlusion of the arterial lumen. "We examined the independent association between serum vitamin D and PTH with multiple subclinical markers of atherosclerosis." (PMID 29088221, 2017). "In this large community-based cross-sectional study, we evaluated the association between serum 25-OHD and PTH concentration with subclinical atherosclerosis in middle-aged and elderly subjects aged ≥50 years." (PMID 29088221, 2017). "On the other hand, suppressing PTH by vitamin D intake might present a potential therapeutic target to prevent PTH-driven endothelial dysfunction, atherosclerosis, and platelet activation as leading causes of cardiac ischemia and HF development." (PMID 34222377, 2021). "Moreover, several studies have shown that IS is associated with atherosclerosis, cardiovascular events, and skeletal resistance to parathyroid hormone (PTH) in dialysis patients." (PMID 33668430, 2021). "PTH also has been reported to be associated with atherosclerosis and cardiovascular diseases." (PMID 34641970, 2021). "The aim of the current study was to investigate the independent association of serum vitamin D and PTH with multiple subclinical markers of atherosclerosis and suggest possible pathways underlying this association between these factors and CVD morbidity and mortality." (PMID 29088221, 2017). "In addition, several studies have supported the notion that increased PTH levels cause atherosclerosis or vessel wall dysfunction." (PMID 28115793, 2017). "Among the factors involved in mineral metabolism, different PTH values directly interfere with the survival of patients on dialysis, by increasing the risk of cardiovascular death, since it is associated with the acceleration in the formation of atherosclerosis and arterial calcifications." (PMID 35510838, 2023). "Since endothelial dysfunction is a precursor of atherosclerosis and is associated with coronary events and because inflammation plays an important role in the pathogenesis of MI, these findings may explain the links between P and PTH levels, and MI." (PMID 25494334, 2014). "The key role of parathyroid hormone (PTH) in both atherosclerosis and aortic valve calcification cannot be ignored." (PMID 40870420, 2025). "In advanced CKD, high parathyroid hormone (PTH) secretion affects pro-inflammatory cytokines and vascular remodeling: elevated PTH levels transform VSMCs into osteoblast-like cells, leading to atherosclerosis and vascular calcification." (PMID 39057644, 2024). "Exercise-induced increases in PTH levels suggest a potential mechanism for exercise-related atherosclerosis, with repeated exposure to elevated PTH post-exercise potentially accelerating coronary atherosclerosis." (PMID 39518662, 2024). "The results showed the top 16 KEGG pathways involving downregulated overlapping genes, which included hepatocellular carcinoma, fluid shear stress and atherosclerosis, parathyroid hormone synthesis, secretion and action and so on." (PMID 36555290, 2022). "Compared to acute short cold stress, there were additional enriched pathways such as rheumatoid arthritis, apoptosis, fluid shear stress and atherosclerosis, parathyroid hormone synthesis, secretion and action, and endocrine resistance pathways." (PMID 36155652, 2022). "Taken together our data point to the role of PTH as a marker of atherosclerosis in PHPT patients not only for large vessels but also for small vessels, as it has been suggested also in the general population." (PMID 30410012, 2018). "Although calcium and phosphate homeostasis is tightly regulated by vitamin D and parathormone (PTH), less attention has been paid to their potential involvement in the pathogenesis of atherosclerosis or as predictors of cardiovascular disease." (PMID 28840128, 2017).